NPTN (neuroplastin)
Description:
Accessory subunit of plasma membrane calcium-transporting ATPase ATP2B2/PMCA2 that stabilizes the transporter at the cell surface (By similarity). Also acts as a chaperone for ATP2B1; stabilizes ATP2B1 and increases its ATPase activity. Probable homophilic and heterophilic cell adhesion molecule involved in long term potentiation at hippocampal excitatory synapses through activation of p38MAPK (By similarity). May also regulate neurite outgrowth by activating the FGFR1 signaling pathway (By similarity). May play a role in synaptic plasticity (By similarity). Promotes localization of XKR8 at the cell membrane.
Synonyms: SDFR1; SDR1; GP55; GP65; np65; np55
Tractability: Antibody: UniProt places it where antibodies can reach, with medium confidence; UniProt predicts a signal peptide or a membrane-spanning region; its Gene Ontology location is reachable by antibodies, with medium confidence; the Human Protein Atlas places it where antibodies can reach. PROTAC: ubiquitination databases record sites on it; its protein half-life has been measured.
Gene: Protein-coding gene on chromosome 15 (73,560,003 to 73,634,134, reverse strand). Ensembl gene ENSG00000156642.
Subcellular location: Cell membrane; Postsynaptic density (Isoform 2)
Subcellular location (Human Protein Atlas): Plasma membrane
Pathways (Reactome):
Neuronal System: GABA receptor activation
Gene Ontology:
Molecular function: protein binding; cell adhesion molecule binding; cell-cell adhesion mediator activity; type 1 fibroblast growth factor receptor binding
Biological process: axon guidance; dendrite self-avoidance; homophilic cell-cell adhesion; intracellular calcium ion homeostasis; long-term synaptic potentiation; negative regulation of cytokine production; positive regulation of cytosolic calcium ion concentration; positive regulation of fibroblast growth factor receptor signaling pathway; positive regulation of long-term neuronal synaptic plasticity; positive regulation of neuron projection development; positive regulation of protein phosphorylation; modulation of chemical synaptic transmission; regulation of multicellular organismal process
Cellular component: cell surface; axon; immunological synapse; plasma membrane; postsynaptic density; presynaptic membrane; dendrite
Genetic constraint (gnomAD): Loss-of-function variants: 5 observed, 36.54 expected, observed/expected ratio (o/e) 0.14, 90% interval 0.071 to 0.29. The upper end of that interval is the gene's LOEUF score, 0.29, which puts it in group 1 of 6, group 1 being the genes least tolerant of losing a copy. Missense variants: 286 observed, 505.31 expected, observed/expected ratio (o/e) 0.57, 90% interval 0.51 to 0.62. Synonymous variants: 179 observed, 196.25 expected, observed/expected ratio (o/e) 0.91, 90% interval 0.81 to 1.03.
Homologues: Orthologues: chimpanzee NPTN (100% identical), macaque NPTN (99% identical), rat Nptn (96% identical), mouse Nptn (95% identical), pig NPTN (95% identical), guinea pig NPTN (94% identical), rabbit NPTN (88% identical), dog NPTN (83% identical), tropical clawed frog nptn (71% identical), zebrafish nptnb (67% identical), zebrafish nptna (44% identical), Drosophila melanogaster Bsg (28% identical), and 1 more. Paralogues in human: BSG (39% identical), EMB (19% identical), VSTM2L (10% identical).